GPR183 (G protein-coupled receptor 183)
Diseases named in the same sentence as GPR183 in open-access papers (continued):
Sharing a sentence is not in itself a finding about the gene and the disease.
bronchiolitis obliterans (1 paper, 2023). "This concept is supported by an observation in a mouse lung transplant model of bronchiolitis obliterans, a condition that frequently causes lung damage in patients with cGVHD, where inhibition of GPR183/EBI2 with a highly selective inhibitor reduces pulmonary lymphoid lesions and lung damage." (PMID 37129971, 2023).
Crohn disease (1 paper, 2022). A gastrointestinal disorder characterized by chronic inflammation involving all layers of the intestinal wall, noncaseating granulomas affecting the intestinal wall and regional lymph nodes, and transmural fibrosis. "Among these, we found increased GPR183 expression, not only in colon biopsies from UC but also from Crohn’s disease patients." (PMID 36389671, 2022). "Using publicly available microarray data of colon biopsies, we found that, like GPR183, GPR18 transcripts also were increased in the colons of UC and Crohn’s disease patients." (PMID 36389671, 2022). "They found that GPR183 mRNA as well as CH25H and CYP7B1 were increased in colon biopsy samples of UC patients vs. healthy controls, although Crohn’s disease patients and responsiveness to TNF blockade were not included in that analysis." (PMID 36389671, 2022).
Epstein-Barr virus infection (1 paper, 2024). An infection that is caused by Epstein-Barr virus. "A similar relation has been proposed for GPR183 and Epstein-Barr virus infections." (PMID 39545055, 2024).
fungal infection (1 paper, 2025). "We identify a non-redundant role for GPR183-mediated chemotaxis in organizing TH2 cells within these microanatomical structures that emerge during chronic fungal infection." (PMID 40766699, 2025). "S4, P and Q), indicating that GPR183 does not affect CD4+ T cell differentiation in the setting of fungal infection." (PMID 40766699, 2025). "As GPR183 has been reported to promote eosinophil and macrophage entry to lung tissues in inflammatory settings, we asked whether GPR183 controlled TH2 lung entry during fungal infection." (PMID 40766699, 2025).
HCMV infection (1 paper, 2017). "Network analysis of the differentially expressed genes in cord DCs, revealed among the downregulated genes after 16 h of HCMV infection several GPCRs with pro-inflammatory response function (ADORA3, ARRB1, C5AR1, CXCR4, GPR34, GPR183, GRK3, and RGS18)." (PMID 28993767, 2017). "In addition to these, HCMV infection of cord DCs resulted in a suppression of several other GPCRs [including GPR68, GPR183 (EBI2), and GPR146] that, together with C5AR1, CXCR4, and RGS18, have been shown to be highly enriched in unstimulated macrophages and dendritic cells." (PMID 28993767, 2017).
Hyperglycemia (1 paper, 2020). An increased concentration of glucose in the blood. "Our results thus strengthen the contention that GPR183 plays an important role in the innate immune control of Mtb irrespective of hyperglycemia." (PMID 33240287, 2020).
Hypertension (1 paper, 2025). The presence of chronic increased pressure in the systemic arterial system. "Although poorly explored, previous studies have shown that GPR183 expression was increased in mice with hypertension, and renal biopsies from individuals with hypertensive nephropathy have demonstrated the deficiency of this gene in the endothelium." (PMID 41169019, 2025).
Insulin resistance (1 paper, 2024). Increased resistance towards insulin, that is, diminished effectiveness of insulin in reducing blood glucose levels. "In contrast, male Gpr183–/– mice that also showed significantly higher insulin levels after HFSD were able to compensate for insulin resistance." (PMID 39545055, 2024). "This suggests that Gpr183 has no central role in insulin resistance in female mice, while male mice benefit from the lack of Gpr183." (PMID 39545055, 2024).
MRSA pneumonia (1 paper, 2026). "In a murine MRSA pneumonia model, PTX-trained mice showed reduced bacterial burden, preserved lung barrier integrity, and enhanced immune activation, all of which were reversed by GPR183 inhibition or STING deficiency." (PMID 41546010, 2026).
prostate carcinoma (1 paper, 2020). A carcinoma that arises from epithelial cells of the prostate gland. "The immune score, as well as the expression of CXCR4 and GPR183 in prostate cancer tissues, could be potential indexes for the prognosis of prostate cancer." (PMID 33194726, 2020). "However, no studies have reported any links between GPR183 and prostate cancer." (PMID 33194726, 2020).
pulmonary fungal infection (1 paper, 2025). "Here, we identify CD11c+Ly6C− lung macrophages that emerge during pulmonary fungal infection as major 25-HC producers establishing GPR183-dependent chemotaxis to guide TH2 positioning." (PMID 40766699, 2025).
Sepsis (1 paper, 2026). Sepsis is defined as life-threatening organ dysfunction caused by a dysregulated host response to infection. "Weighted gene co-expression network analysis was used to identify gene modules significantly associated with pediatric sepsis, and 237 high-confidence biomarkers were screened based on 14 machine learning models, among which RORA and GPR183 stood out in multiple models." (PMID 42023222, 2026).
Splenomegaly (1 paper, 2022). Abnormal increased size of the spleen. "We also assessed the role of GPR183 in B1 cells in an indomethacin challenge model, where all mice had splenomegaly, suggesting that the indomethacin caused systemic inflammation in both genotypes of mice." (PMID 35159303, 2022).
tumor (17 papers, 2013 to 2026). "In conclusion, CXCR4 and GPR183 were down-regulated in PCa tumors, and both of these genes were associated with tumor purity and immune cell infiltration." (PMID 33194726, 2020). "These oxysterols regulate ILC migration by binding to the G-protein coupled receptor 183 (GPR183), influencing their positioning and activity within the tumor." (PMID 40270603, 2025). "The expression level of CXCR4 was found to be similar between PCa tumor and normal tissues; however, GPR183 was down-regulated in the PCa tumor tissues as compared with the normal tissues." (PMID 33194726, 2020). "Next, we explored the unique function of WDR45B+ TAMs compared to the other TAMs, and found upregulation of several known tumor-promoting genes, such as LGALS2 and GPR183." (PMID 38414027, 2024). "Genetic depletion and pharmacological inhibition of GPR183 impaired ADCP initiation, cytoskeleton remodeling and cell migration in 2D and 3D spheroid B-NHL co-cultures, and disrupted macrophage-mediated control of tumor growth in B-NHL CAM xenografts." (PMID 37153563, 2023). "In summary, our results support a role for GPR183 in the recognition and elimination in vitro and in vivo of malignant B cells by activated macrophages, upon concomitant targeting of CD20, CD47 and PI3Kδ in tumor cells." (PMID 37153563, 2023). "We found that CD8-GNLY effector T cells in high tumor infiltration group displayed increasing level of the serine/threonine kinase PIM family (PIM2 and PIM3), NR4A2/3, KLF4/6, BCL2, GPR183 and COTL1 compared to the ones from HD and low tumor infiltration group." (PMID 36532059, 2022). "Strikingly, treatment with metformin might reduce tumor growth, mainly by inducing the expression of a set of genes FOSB, EGR1, ZFP36, GPR183, ATF3, and NR4A1 which are involved in DNA-binding transcriptional activation, response to hormones and the Dcp1-Dcp2 mRNA-decapping complex." (PMID 39026155, 2024).
infection (16 papers, 2013 to 2025). The state of being infected such as from the introduction of a foreign agent such as serum, vaccine, antigenic substance or organism. "In vivo GPR183 deficiency results in disorganized distribution of ILC3 in mesenteric lymph nodes and reduces ILC3 accumulation in the intestine, and thus GPR183-deficient mice are more susceptible to infection by pathogenic intestinal bacteria." (PMID 35216425, 2022). "Together, these results suggest that the downregulation of genes associated with adhesion molecules, especially genes encoding the critical receptors S1PR2 and GPR183, may contribute to the loss of GCs and disrupt of B/T cell interaction at the severe stage of infection." (PMID 37146079, 2023). "In inflamed lung tissues, GPR183, a well-established chemotactic receptor in lymphoid organs, guides recruited T cells towards infection sites, thereby shaping local immune responses." (PMID 40766699, 2025). "Here, we show that GPR183 on TH2 cells senses macrophage-derived oxysterols to guide positioning towards infection sites and establish local immunosuppressive niches." (PMID 40766699, 2025). "Following infection with M. tuberculosis, mice with diet-induced dysglycemia had reduced lung expression of Cyp7b1 and Gpr183, accompanied by impairment in macrophage migration to the lungs and reduced control of infection." (PMID 38693938, 2024). "Extra-follicular B cell responses serve as early antibody sources during infection, maintaining elevated levels of G protein-coupled receptor 183 (GPR183) to avoid the GC milieu and increasing CXCR4 expression to facilitate their migration to lymph nodes." (PMID 38045685, 2023). "GPR183, also known as Epstein–Barr virus-induced G protein coupled-receptor 2, was discovered in the 1990s as one of the genes that were upregulated upon infection with Epstein–Barr virus in Burkitt’s Lymphoma cell lines." (PMID 35053318, 2022). "Local dermal inflammation as a result of MPXV infection may result in an increased level of oxysterols, promoting the migration of GPR183+ MPXV-specific CD8+ T cells to the site of infection." (PMID 40348752, 2025). "B cell transcriptomics indicated significant downregulation of several adhesion molecules during infection, including S1PR1, S1PR2, ITGA4, ITGA6, GPR183, and CCR7." (PMID 37146079, 2023). "Three of these genes, S1PR1, GPR183, and CCR7, showed a trend of continuous downregulation throughout infection, with fold-changes of -1.68, -2.30, and -1.64 at D8, respectively." (PMID 37146079, 2023). "Genes involved in the control of cell migration were also represented in the HP1 list (e.g. Ccr2, Ccr5, Itga1, Itgb1, Gpr183, Rgs16), with some having an essential role in the recruitment of CD8 T cells in the lung following infection by a pathogen." (PMID 27883012, 2016). "Mice lacking GPR183 had significantly increased lung Mtb burden and dysregulated IFNs during early infection." (PMID 33240287, 2020).
neurodegenerative disease (6 papers, 2015 to 2025). A disorder of the central nervous system characterized by gradual and progressive loss of neural tissue and neurologic function. "Four genes inside these degenerative diseases also showed differential expression among ages: CTCL (G50 vs G60), CALM1 (G50 vs G70), GPR183, and GRIN2A (G60 vs G70)." (PMID 33576945, 2021).
bacterial infections (3 papers, 2022 to 2026). "Collectively, our findings uncover a previously unrecognized immunomodulatory function of PTX and highlight the therapeutic potential of targeting the GPR183-STING axis to enhance trained immunity against resistant bacterial infections." (PMID 41546010, 2026). "The leading edge genes driving the enrichment of the inflammatory response pathway in response to bacterial infections included several relevant for T‐cell activation (IL1B, CCL5, TNFSF10, GPR183, CD69, SELL), suggesting that cDC2s were undergoing conventional maturation." (PMID 34333764, 2022).
cardiovascular diseases (3 papers, 2015 to 2022). "Antagonists of GPR183 have been suggested to be tested in paradigms relevant for cardiovascular diseases." (PMID 28407751, 2017).
metabolic disease (3 papers, 2015 to 2024). A congenital disorder (due to inherited enzyme abnormality) or acquired (due to failure of a metabolically important organ) disorder resulting from an abnormal metabolic process. "The G protein‐coupled receptor GPR183/EBI2, which is activated by oxysterols, is a therapeutic target for inflammatory and metabolic diseases where both antagonists and agonists are of potential interest." (PMID 34270165, 2021). "Despite the altered levels of oxysterols in metabolic diseases and our current insight into the role of GPR183 in the intestinal immune response, combined with a recently proven expression of GPR183 in rat and human islets, surprisingly little is known about GPR183 in metabolic diseases." (PMID 39545055, 2024).
hematological cancers (1 paper, 2024). "Among these GPCRs, GPR85, GPR65, and GPR183 have varying numbers ofstudies in the field of hematological cancers and pediatric ALL." (PMID 39698279, 2024).
GPR183 also shares sentences with these, for which no sentence is quoted: cancer (9 papers); multiple sclerosis (9); rheumatoid arthritis (4); demyelinating disease (2); diabetes (2); inflammation (2); atherosclerosis (1); central nervous system infectious diseases (1); chronic lymphocytic leukemia (1); colorectal cancer (1); dermatomyositis (1); diffuse large B-cell lymphoma (1); dyslipidemia (1); emphysema (1); hypertensive nephropathy (1); Immunodeficiency (1); intestinal diseases (1); liver steatosis (1); lupus nephritis (1); malaria (1); nasal polyps (1); neuroblastoma (1); non-alcoholic steatohepatitis (1); osteoporosis (1); ovarian carcinoma (1); ovarian hyperstimulation syndrome (1); pancreatic cancer (1); Pulmonary hemorrhage (1); pulmonary hypertension (1); pulmonary tuberculosis (1).
A further 7 diseases each share a sentence with GPR183 in 1 paper.